ZNF394 (zinc finger protein 394)
Description:
May be involved in transcriptional regulation.
Synonyms: ZKSCAN14; FLJ12298; ZSCAN46
Tractability: PROTAC: UniProt records ubiquitination sites on it; ubiquitination databases record sites on it.
Gene: Protein-coding gene on chromosome 7 (99,473,877 to 99,504,918, reverse strand). Ensembl gene ENSG00000160908.
Subcellular location: Nucleus
Subcellular location (Human Protein Atlas): Nucleoplasm; Cytosol
Pathways (Reactome):
Gene expression (Transcription): Generic Transcription Pathway
Gene Ontology:
Molecular function: protein binding; DNA-binding transcription factor activity, RNA polymerase II-specific; RNA polymerase II cis-regulatory region sequence-specific DNA binding
Biological process: regulation of transcription by RNA polymerase II; regulation of DNA-templated transcription
Cellular component: nucleoplasm; nucleus
Genetic constraint (gnomAD): Loss-of-function variants: 21 observed, 24.36 expected, observed/expected ratio (o/e) 0.86, 90% interval 0.61 to 1.24. The upper end of that interval is the gene's LOEUF score, 1.24, which puts it in group 5 of 6, group 1 being the genes least tolerant of losing a copy. Missense variants: 683 observed, 740.03 expected, observed/expected ratio (o/e) 0.92, 90% interval 0.87 to 0.98. Synonymous variants: 294 observed, 282.78 expected, observed/expected ratio (o/e) 1.04, 90% interval 0.94 to 1.14.
Homologues: Orthologues: chimpanzee ZNF394 (98% identical), macaque ZNF394 (95% identical), rabbit ZNF394 (67% identical), guinea pig ZNF394 (63% identical), dog ZNF394 (62% identical), mouse Zkscan14 (62% identical), rat Atp5mf (41% identical). Paralogues in human: ZKSCAN8 (37% identical), ZNF397 (36% identical), ZSCAN30 (35% identical), ZSCAN12 (35% identical), ZNF263 (34% identical), ZKSCAN4 (34% identical), ZSCAN26 (34% identical), ZSCAN21 (34% identical), ZKSCAN3 (34% identical), ZNF165 (34% identical), ZNF449 (33% identical), ZSCAN22 (33% identical), and 18 more.
Diseases named in the same sentence as ZNF394 in open-access papers:
ZNF394 is named in the same sentence as 1 disease in open-access papers, as found by Europe PMC text mining. Sharing a sentence is not in itself a finding about the gene and the disease.
ZNF394 shares sentences with these, for which no sentence is quoted: connective tissue disorder (1 paper).